SPMAP2L (sperm microtubule associated protein 2 like)
Synonyms: THEGL
Tractability: No criterion of Open Targets' tractability assessment is met for any kind of drug.
Gene: Protein-coding gene on chromosome 4 (56,530,606 to 56,603,507, forward strand). Ensembl gene ENSG00000249693.
Subcellular location (Human Protein Atlas): Principal piece
Genetic constraint (gnomAD): Loss-of-function variants: 40 observed, 40.35 expected, observed/expected ratio (o/e) 0.99, 90% interval 0.77 to 1.29. The upper end of that interval is the gene's LOEUF score, 1.29, which puts it in group 5 of 6, group 1 being the genes least tolerant of losing a copy. Missense variants: 508 observed, 540.84 expected, observed/expected ratio (o/e) 0.94, 90% interval 0.87 to 1.01. Synonymous variants: 182 observed, 203.22 expected, observed/expected ratio (o/e) 0.9, 90% interval 0.79 to 1.01.
Homologues: Orthologues: chimpanzee SPMAP2L (99% identical), macaque SPMAP2L (94% identical), dog SPMAP2L (61% identical), rabbit SPMAP2L (59% identical), pig SPMAP2L (55% identical), guinea pig SPMAP2L (55% identical), mouse Spmap2l (55% identical), rat Spmap2l (54% identical), Drosophila melanogaster Theg (17% identical). Paralogues in human: SPMAP2 (17% identical).
Diseases named in the same sentence as SPMAP2L in open-access papers:
SPMAP2L is named in the same sentence as 1 disease in open-access papers, as found by Europe PMC text mining. Sharing a sentence is not in itself a finding about the gene and the disease.
SPMAP2L shares sentences with these, for which no sentence is quoted: tumour (1 paper).